NRAS (NRAS proto-oncogene, GTPase)
Diseases named in the same sentence as NRAS in open-access papers (continued):
Sharing a sentence is not in itself a finding about the gene and the disease.
cutaneous melanoma (continued). "For instance, The Cancer Genome Atlas (TCGA) defined three genomic subtypes of cutaneous melanoma based on the mutation status of BRAF, NRAS, NF1, and a fourth subgroup termed triple wild-type." (PMID 32517051, 2020). "In the majority of cases UV-induced human skin melanoma is characterized by founder somatic mutations of two oncogenes, BRAF and NRAS." (PMID 31391014, 2019). "c-KIT mutations have been detected in almost 2–7% of conjunctival melanomas and they are mutually exclusive with NRAS and BRAF mutations, as in cutaneous melanoma." (PMID 31683701, 2019). "We validated previous reports that the commonly known mutations in cutaneous melanoma, including BRAF, NRAS, NF1, GNAQ and GNA11, were rarely mutated in mucosal melanomas." (PMID 30847022, 2019). "RAC1 P29 is the third most commonly mutated codon in human cutaneous melanoma, after BRAF V600 and NRAS Q61." (PMID 31257073, 2019). "Examining the preferred single-base substitutions collated from NRAS and BRAF in mucosal melanoma revealed a different mutation profile than cutaneous melanoma, suggesting different etiologies for both malignancies." (PMID 31398831, 2019). "Cutaneous melanoma can be divided into molecular subgroups (BRAF mutated, NRAS mutated, NF1 mutated, triple wild-type) and show the typical ultra violet (UV) signature (C > T transition)." (PMID 31500314, 2019). "The frequency of BRAF, NRAS and KIT mutations in CjM is more similar to cutaneous melanoma than uveal/mucosal melanoma." (PMID 31683701, 2019). "We also demonstrated that mutations in NRAS and BRAF in mucosal melanoma are different from the ones found in cutaneous melanoma, suggesting the existence of genotoxic agents in mucosal melanoma that remain to be identified." (PMID 31398831, 2019). "In CjM, NRAS mutations are mutually exclusive with BRAF mutations, similarly to cutaneous melanoma, in which concomitant BRAF and NRAS mutations occur in less than 0.6% of cases." (PMID 31683701, 2019). "BRAF and NRAS genes, which encode mitogen-activated protein kinase (MAPK) pathway constituents, are recurrently mutated in cutaneous melanoma." (PMID 29992995, 2018). "The majority of human cutaneous melanomas are driven in part by constitutive activation of the MAPK pathway through mutation of genes such as BRAF, NRAS, NF1, KIT, GNAQ, and GNA11, often in a mutually exclusive pattern." (PMID 30188888, 2018). "The role of BRAF and CRAF kinases in NRAS-induced cutaneous melanoma was assessed by inactivating Raf genes in the Tyr::NRASQ61K/o;Ink4a+/− transgenic mouse model." (PMID 28497782, 2017). "The occurrence of NRAS and PTEN mutations were previously found to occur rarely in cutaneous melanoma." (PMID 29383127, 2017). "Management strategies are proposed for presentation of suspected melanoma of the skin and the central nervous system in patients with CMN, including use of oral mitogen‐activated protein kinase kinase inhibitors in NRAS‐mutated tumours." (PMID 28078671, 2017). "We also found that there were 206 genes that negatively correlated with HRAS expression significantly overlapped with genes positively correlated with KRAS/NRAS in cutaneous melanoma." (PMID 29349077, 2017). "The PI3K/AKT signal transduction pathway is considered a potential co-target for BRAF and NRAS mutant cutaneous melanoma." (PMID 28938534, 2017). "Treatment of MEKi combined with AKTi has been used to treat BRAF-mutant, BRAF-WT and NRAS-mutant cutaneous melanoma patients." (PMID 28938534, 2017). "Constitutive expression of an activated form of human NRAS (NRASQ61K) in the melanocytic lineage results in spontaneous cutaneous melanoma development, a process that is accelerated on an Ink4a-deficient background." (PMID 28497782, 2017).
cutaneous melanoma (continued). "For example, the mutex analysis between RAC1 and NRAS in skin melanomas confirms the relevance of the role of RAC1, which is co-mutated with NRAS, in gain-of-function oncogenic GTP mediated events." (PMID 26860319, 2016). "Instead of common occurence of BRAF or NRAS mutations in cutaneous melanoma, few cases of UM harbor BRAF and NRAS mutations." (PMID 26940009, 2016). "Since the discovery of gain of function mutations in the proto-oncogenes NRAS and BRAF, thousands of human skin melanoma samples have been analyzed, and the estimated incidence of NRAS and BRAF mutations are 18 % and 41 %, respectively." (PMID 26141748, 2015). "Recent combined data analysis from various reports so far has disclosed a prevalence of 5% for BRAF and 14% for NRAS oncogenic mutations in all types of mucosal melanomas, strikingly in contrast to the BRAF prevalence of 56–59% in cutaneous melanomas." (PMID 25695059, 2015). "By contrast, as previously demonstrated, gene mutations for cutaneous melanomas were irrelevant in vulvar melanomas (BRAF, NRAS), indicating that these two diseases have a different origin." (PMID 24535703, 2014). "Frequently, NRAS and BRAF mutations have been observed in cutaneous melanoma and in subsets of mucosal melanoma." (PMID 25120707, 2014). "Mutations in v-Raf murine sarcoma viral oncogene homolog B1 (BRAF), NRAS and Kit are among the most prevalent driving aberrations in cutaneous melanoma with 15-20% affecting the NRAS oncogene." (PMID 25277205, 2014). "Molecular profiling may further support treatment tailoring by identifying actionable mutations (e.g., c-KIT, NRAS, or BRAF), although their prevalence is lower than in skin melanomas." (PMID 40875164, 2025). "Analysis of cutaneous melanoma data in The Cancer Genome Atlas has shown that the prevalence of BRAF mutations is ~45% (90% of which is V600E), followed by a prevalence of the NRAS oncogene exon 3/codon 61 of 15–20%, while other RAS mutations are less frequent (KRAS, HRAS)." (PMID 40361349, 2025). "The presence of the NRAS mutation was not evaluated in the population during studies on effectiveness of adjuvant immunotherapy with ICIs in cutaneous melanoma." (PMID 39148899, 2024). "However, the frequency of BRAF, NRAS and Kit mutations in ARM is lower than that of cutaneous melanoma which can also be inferred by our study." (PMID 38180677, 2024). "As mentioned, the most frequently mutated genes in cutaneous melanoma are BRAF and NRAS." (PMID 38396984, 2024). "NRAS and BRAF mutations are frequently observed in cutaneous melanoma." (PMID 37861097, 2024). "BRAF and NRAS mutations have been reported in 41% and 18% of human cutaneous melanomas, respectively, and KIT mutations in 8.6–25% of acral/mucosal/chronically sun-damaged skin melanomas." (PMID 38397192, 2024). "Among cutaneous melanoma cases, 76% had BRAF mutations, and 8% had NRAS mutations." (PMID 39564955, 2024). "Additionally, non-cutaneous melanomas are characterized by lower rates of targetable mutations in BRAF and NRAS." (PMID 39416390, 2024). "NRAS and KIT mutations are more frequently observed in PMME than in cutaneous melanoma." (PMID 37861097, 2024). "In contrast, the prevalence of NRAS and KIT mutations is higher in PMME than in cutaneous melanoma." (PMID 37861097, 2024). "NRAS mutations have been identified in about 20% of CMs, as similarly observed in skin melanomas, whereas these mutations do not typically occur in posterior uveal melanomas." (PMID 37761808, 2023). "Globally, the infrequent rate of BRAF V600E mutation observed in MM limits the efficacy of BRAF inhibitors, largely used in cutaneous melanoma, while the higher NRAS and c-KIT mutations rates make them potentially susceptible to NRAS and c-Kit target therapies." (PMID 35059992, 2022).
cutaneous melanoma (continued). "We identified 27 cutaneous melanoma cases with BRAF mutations, of which 21 (78%) could also be detected by the Idylla BRAF and BRAF/NRAS cartridges if run." (PMID 35627184, 2022). "The following panel of oncomirs contains the miRNAs (miR-21, miR-10b, miR125b, miR-135b, miR-146a, miR-150, miR-155, miR-205, miR-211, miR-221, miR-222) that regulate tumour promoter genes associated with cutaneous melanoma (RAS/MAK, MITF, PI3K-AKT, P27Kip, NRAS, TYRP1, WEE1, LATS2)." (PMID 36614156, 2022). "However, genetic evidence argues these tumors mostly originate from cutaneous sites, as they demonstrate a similar distribution of BRAF, NRAS and NF1 mutations to cutaneous melanoma." (PMID 35565222, 2022). "YAP1 expression was detected in cutaneous melanoma cell lines lacking a GNAQ/11 mutation (but harboring BRAF or NRAS mutations instead), and in human cutaneous melanoma tissue where a high expression was related to worse survival." (PMID 33798262, 2021). "For instance, the majority of cutaneous melanoma harbor mutations of B-Raf proto-oncogene, serine/threonine kinase (BRAF), NRAS proto-oncogene, GTPase (NRAS) and neurofibromin 1 (NF1) as well as loss of cyclin dependent kinase inhibitor 2A (CDKN2A) encoding P16NK4a." (PMID 34830903, 2021). "Among the patients without NRAS mutation, the ORRs of anti-PD-1 monotherapy were 23.9% for cutaneous melanoma and 13.7% for noncutaneous melanoma as follows: 12.1% in acral melanoma and 16.7% in mucosal melanoma." (PMID 34290710, 2021). "NRAS mutations are amenable to MEK inhibitor therapy, as has been shown for cutaneous melanoma." (PMID 34071371, 2021). "The mutation profile of melanoma of unknown primary is similar to cutaneous melanoma, with frequent BRAF (~50%) and NRAS (~20%) mutations." (PMID 32718045, 2020). "Unlike cutaneous melanoma, uveal melanoma is not characterised by frequent BRAF or NRAS mutations, so that advances in targeted therapy for cutaneous melanoma are not applicable to metastatic uveal melanoma." (PMID 31323802, 2019). "Although NRAS mutations in cutaneous melanoma do not present the typical UV signature, Q61 mutations have previously been linked to UV." (PMID 31398831, 2019). "A relevant role for NF1 mutations in cutaneous melanomas lacking conventional (i.e. BRAF or NRAS) activating mutations has been already highlighted by other studies." (PMID 28380455, 2017). "A large proportion of cutaneous melanomas harbor mutations in genes that are part of the mitogen activated protein kinase (MAPK) pathway (i.e., BRAF and NRAS), which deregulate several important biological processes (proliferation, senescence, survival, and differentiation) in melanocytes." (PMID 27057633, 2016). "The cytotoxic effects of bromodomain inhibition reported in cutaneous melanoma cells were independent of the mutational status of BRAF or NRAS." (PMID 26397223, 2015). "Constitutive MAPK activation seems to be a common event in both skin and uveal melanomas, although it occurs through different mechanisms: in skin melanoma, through BRAF and NRAS activating mutations, and in uveal melanoma MAPK activation can occur through GNAQ activating mutations." (PMID 23904987, 2013). "Skin melanoma patients without signs of chronic sun-induced damage are prone to have mutations in the BRAF or NRAS gene Breast cancer and colon cancer have been found to be more aggressive in patients with low SES and in minority groups." (PMID 22957007, 2012). "Whereas mutant BRAF and NRAS are responsible for the activation of the RAS/RAF/MEK/ERK pathway in most cutaneous melanoma, mutations in these genes are usually absent in UM." (PMID 19568237, 2009).
cutaneous melanoma (continued). "This deferred selection for MAP-kinase pathway mutations results in an unexpected heterogeneity in the primary tumors, with BRAF V600E mutation or NRAS Q61 mutations present in some areas of the tumor and absent in others, a finding that is highly unusual for cutaneous melanomas." (PMID 39034322, 2024). "Hotspot mutations predominantly in the V600 codon of BRAF and the Q61 codon of NRAS, as well as loss-of-function events in NF1, led to a cascade of perturbations causing upregulation of the MAPK pathway, the most deregulated signalling pathway in cutaneous melanoma." (PMID 38201222, 2023). "Mutations in BRAF and NRAS are not so uncommon among mucosal melanomas (up to 20% of cases); rather, they have peculiar features that are radically different from those observed in cutaneous melanomas." (PMID 35008570, 2021). "BRAF and NRAS mutations, frequently occurring in cutaneous melanoma, do not occur in posterior UM." (PMID 32718045, 2020). "According to the Cancer Genome Atlas (TCGA) classification, cutaneous melanoma comprises four main subtypes: BRAF-mutant (~50%), NRAS-mutant (~20%), NF1-mutant (~10–15%) and triple negative/wild-type (~10–15%)." (PMID 41465101, 2025). "In cutaneous melanoma, the most frequently genetic subtypes are mutant serine/threonine-protein kinase B-raf (BRAF) and GTPase NRas (NRAS), neurofibromin 1 (NF1) and triple wild-type." (PMID 41197182, 2025). "Recently, targeted therapies, including inhibitors of c-KIT, NRAS/MEK or BRAF, and immunotherapies, including anti-CTLA-4 and anti-PD-1/PD-L1 antibodies, have revolutionized the treatment of cutaneous melanoma." (PMID 38326751, 2024). "Aberrations in kinases such as proto-oncogene BRAF (exons 11 and 15; p.V600E), NRAS (exons 2 and 3; codons 12, 13, and 61), or KIT (exons 11, 13, 17, and 18) are key factors in human skin melanomas, regulating melanocyte proliferation survival and apoptosis." (PMID 38397192, 2024). "We found that NRAS mutation was associated with poorer overall survival (OS), and TMB was predictive of dual ICI response, suggesting that tumor genetics may help serve as an informative biomarker predictive of ICI response and clinical outcomes for cutaneous melanoma." (PMID 38611025, 2024). "Additional investigation into “triple wild-type” cutaneous melanomas and their reliance on Ras/MAPK signaling is an area for further study, and poor outcomes in NRAS mutant tumors highlight an urgent, unmet clinical need for therapeutic development." (PMID 38611025, 2024). "Like in skin melanomas, the frequency of CNAs in CMs appears to vary depending on the genetic background and has been shown to be relatively higher in BRAF/NRAS-wildtype tumors." (PMID 37761808, 2023). "Ten years after transplantation, he was diagnosed with cutaneous melanoma arising from the nasal dorsum and left cervical lymph node metastases with extracapsular extension, stage IIIC (BRAF/NRAS/c-kit wildtype)." (PMID 36941274, 2023). "Blocking ERK activation rescued IFNγ-mediated apoptosis in 17 of 23 (~ 74%) cell lines representing BRAF, NRAS, NF1 mutant, and triple wild type subtypes of cutaneous melanoma." (PMID 37803324, 2023). "Overall, alterations in BRAF, NRAS, NF1 and KIT are present in 93% of human cutaneous melanomas in a mutually exclusive pattern, although a small fraction of tumors harbor alterations in several of these genes." (PMID 35234863, 2022). "In this regard, the Cancer Genome Atlas (TCGA) program has established a framework of genomic classification for cutaneous melanomas as BRAF, NRAS, NF1, and Triple Wild-Type (WT), and serves as a guide when making decisions about therapy." (PMID 35844619, 2022). "Mutations in KIT, NF1 and SF3B1 genes are more frequently seen in mucosal melanomas, while alterations to NRAS and BRAF genes are more common in cutaneous melanomas." (PMID 34209084, 2021).
cutaneous melanoma (continued). "As an example, based on exome and genome sequencing studies, the TCGA Network has classified cutaneous melanoma into four distinct molecular subtypes: BRAF-mutant, NRAS-mutant, NF1-mutant, and BRAF/NRAS/NF1 wild-type (triple-wild-type group)." (PMID 34123788, 2021). "According to the report, cutaneous melanoma can be classified into four subtypes: mutant BRAF; mutant NRAS; mutant NF1; and the triple-wild-type, which is characterized by a lack of hot-spot BRAF, N/H/KRAS, or NF1 mutations." (PMID 32028967, 2020). "This would explain the high frequency of NRAS Q61 and BRAF V600 mutants in cutaneous melanoma where the MAPK pathway is playing such a significant role." (PMID 31398831, 2019). "These included 11 BRAFV600-mutant, 10 NRAS-mutant and 10 BRAF/NRAS wild type (BRAF/NRASWT) cutaneous melanoma cell lines, and 8 GNAQ/11-mutant UVM cell lines." (PMID 29977240, 2018). "Few studies have focused on the transcriptional level of RAS isoforms (KRAS, NRAS, and HRAS) in cutaneous melanoma." (PMID 29349077, 2017). "The majority (47.6%) of the acral melanoma patients did not exhibit mutations in BRAF, NRAS or NF1, and a substantial portion (28.6% compared to 5.6% in BCH-cutaneous melanoma, p = 2.28e−05) presented a pigmented skin phenotype." (PMID 35840550, 2022). "In line with earlier observations in skin melanoma cells, these effects were independent of the mutational status (GNAQ, GNA11, BAP1, BRAF and NRAS) of the UM and CM cell lines." (PMID 34508176, 2022). "Although these tumors did not originate from the uvea of the eye, B16-F10 cells resemble UM in that they are immunotherapy-resistant, do not harbor classical cutaneous melanoma BRAF, NRAS, or NF1 mutations and the TMB is low." (PMID 34753889, 2022). "In cutaneous melanoma, the effects of Dinaciclib correlated neither with the presence of BRAS or NRAS mutations, nor with CDK2 levels." (PMID 35326726, 2022). "Great support in this direction has been given by the exome sequencing studies of the Cancer Genome Atlas Skin Cutaneous Melanoma (SKCM-TCGA) project that classified cutaneous melanoma into four distinct molecular subtypes: BRAF-mutant, NRAS-mutant, NF1-mutant, and triple-wild-type group." (PMID 34944843, 2021). "We report that, consistent with BRN2 playing a key role as a tumor suppressor in melanomagenesis, its locus is frequently lost in human skin cutaneous melanoma (SKCM) metastases, independently of their NRAS or BRAF status, and that BRN2 status contributes to overall patient survival." (PMID 34140478, 2021). "Cutaneous melanoma is divided into four genomic subtypes: BRAF, NRAS, NF1, and Triple-WT." (PMID 33918490, 2021). "It is estimated that about a third of cutaneous melanomas are triple-negative and have no BRAF, NRAS, or NF1 mutations." (PMID 35008286, 2021). "In the cutaneous melanoma cohort, the PFS for NRAS mutant and wild-type patients were 2.7 months (95%CI: 1.7-3.7) and 7.0 months (95%CI: 4.1-9.9) (P=0.024), and the OS were 13.8 months (95%CI: 3.7-23.9) and 20.4 months (95%CI: 12.7-28.1) (P=0.081), respectively." (PMID 34290710, 2021). "A candidate gene approach with 20 cutaneous melanomas found no variant in BRAF, NRAS, PTEN, KIT, GNAQ, and CDK4." (PMID 31262050, 2019). "Our data indicated that HRAS mRNA expression, but not KRAS or NRAS, was correlated with prognosis in cutaneous melanoma." (PMID 29349077, 2017). "In total, out of the 95 cases (77 oral and 18 cutaneous melanomas), no mutations were found in BRAF, KIT, GNAQ, and CDK4 genes; only three had a positive NRAS mutation and two had a PTEN gene mutation, of which one case had both changes." (PMID 29056717, 2016).